EZH2 (enhancer of zeste 2 polycomb repressive complex 2 subunit)
Diseases named in the same sentence as EZH2 in open-access papers (continued):
Sharing a sentence is not in itself a finding about the gene and the disease.
tumor (continued). "High mRNA expression of CDK1, PCNA, EZH2, BUB1, and CXCR4 in tumor was significantly associated with lower RFS." (PMID 38831458, 2024). "For example, in many studies, EZH2 has been reported to promote the malignant behavior of tumor cells, as well as having significance for Treg development." (PMID 39080807, 2024). "These EZH2 inhibitor induced changes were also observed in the non–tumor-bearing control mice, suggesting that the effect of EZH2 inhibition on the bone marrow is tumor independent." (PMID 38265267, 2024). "Meanwhile, it has been discovered in NSCLC that EZH2 can also promote tumor immune evasion by enhancing HIF-1α induced programmed death ligand 1 (PD-L1) expression." (PMID 38911968, 2024). "Taken together, these results demonstrated that EZH2 is strongly correlated with tumor stemness in skull base chordoma." (PMID 38882008, 2024). "EZH2 (Enhancer of zeste homolog 2) promotes tumor growth and survival through numerous mechanisms and is a promising target for novel therapeutic approaches." (PMID 38791289, 2024). "Another area in which EZH2 has been shown to influence is the tumor microenvironment (TME); the TME comprises a network of intricate interactions between various immune cells and cancer cells." (PMID 39768352, 2024). "Given the function of EZH2 and its relationship with the immune system, EZH2 is widely reported to be involved in the tumor immune microenvironment." (PMID 37268997, 2023). "EZH2 plays a decisive role in immune cells such as T cells, natural killer cells, dendritic cells, and macrophages, which are essential components of the tumor microenvironment." (PMID 35841331, 2023). "To further verify these results in vivo, we constructed a xenograft tumor model in nude mice using BEL7404 cells with stable knockdown of EZH2." (PMID 38008711, 2023). "With the continuous deepening of the research and the gradual extension to the clinic, the molecular mechanism of the anti-tumor effect of EZH2 small molecule inhibitors will be further clarified." (PMID 36672374, 2023). "Our functional results indicate the role of EZH2 in ATC tumor cell proliferation, invasion and migration." (PMID 37175580, 2023). "CRISPR knockout of both HMGA2 and EZH2 in the TNBC cell line MDA-MB-231 blocked primary tumor growth and lung metastasis and restored E-Cadherin in vivo." (PMID 36814601, 2023). "Numerous studies have emphasized the importance of the enhancer of zeste homolog 2 (EZH2) in the growth and development of neoplasms, and mutations in EZH2 have been found in a variety of cancers." (PMID 36672677, 2023). "The transcriptional profile of the GCB subclass is similar to that of light zone (LZ) GC B cells, and the tumor cells harbor various mutations affecting chromatin-modifier genes such as CREBBP and EZH2 (enhancer of zeste homolog 2)." (PMID 36611989, 2023). "By establishing orthotopic nude mice models, we further validated the inhibitory role of CA on tumorigenesis of GBM cells in vivo and its potential values to synergistically potentiate the anti-tumor effects of EZH2 inhibitors." (PMID 38264522, 2023). "Overall, our study indicates that hypoxia can promote the glycolysis and tumor growth of NSCLC by regulating the EZH2/FBXL7/PFKFB4 axis." (PMID 37179372, 2023). "Recently, an increasing number of studies revealed that EZH2 promotes tumor development and progression through its methyltransferase activity-independent functions." (PMID 36642705, 2023). "As a core member of the PcG family, EZH2 plays a vital role in cell proliferation, differentiation and tumor formation through H3K27me3-mediated downstream gene silencing." (PMID 36672374, 2023). "EZH2 is closely related to tumour angiogenesis, and inhibition of EZH2 restored normal angiogenesis in endothelial cells." (PMID 36619221, 2023).
tumor (continued). "Elevated EZH2 level has been associated with reduced expression of MHC class I genes and cytokine genes encoding CXCL9/10, which normally act to attract tumor-infiltrating lymphocytes (TILs)." (PMID 37325482, 2023). "Apart from immune regulation, deeper mechanistic insights about the immune regulation function of EZH2 have been achieved mainly from tumor-related studies." (PMID 36768720, 2023). "Specific inhibition of EZH2 reversed the repression of target genes and eventually suppressed in vivo tumor growth in TH-MYCN mice." (PMID 38069407, 2023). "Together these findings demonstrate that EZH2 knockdown can potentiate senescence-mediated long-term tumor control in PDAC through mobilization of cytotoxic NK and T lymphocyte immunity." (PMID 37142692, 2023). "A growing body of research shows that inhibiting EZH2 with a small molecule inhibitor or gene knockout reduces cancer cell growth and tumor formation." (PMID 35841331, 2023). "HMT enhancer of zeste-2-polycomb repressive complex 2 subunit (EZH2) was found to promote tumor proliferation and transformation when overexpressed in various tumors." (PMID 37631010, 2023). "Previous studies have demonstrated that EZH2 inhibitors regulate the NF-κB p65 pathway and influence anti-inflammatory and anti-tumor processes, but the relevance of EZH2 to the NF-κB pathway has not been investigated in MM." (PMID 37239949, 2023). "EZH2 has been shown to facilitate tumor immune evasion and resistance to ICB therapy in other cancer settings." (PMID 37142692, 2023). "As a result, a combination of a EZH2 inhibitor and a STING agonist synergistically reduced tumor growth in association with an increased CD8+ T-cell infiltration." (PMID 36900330, 2023). "The authors highlight three PKMTs – SETD2, SETD7, and EZH2 – which have been found to suppress tumor growth in various types of cancer." (PMID 38036730, 2023). "EZH2 depletion not only suppressed cell proliferation but also attenuated the capacity of tumor sphere formation in OC cells." (PMID 37210576, 2023). "Based on the current literature, the EZH2 inhibitor tazemetostat harbors potential as an (adjuvant) anti-tumor drug." (PMID 36900361, 2023). "The overexpression of EZH2 leads to the silencing of tumor-suppressor genes, promoting cancer cell proliferation, invasion, and metastasis." (PMID 37445833, 2023). "The results of immunohistochemical experiments based on clinical samples showed that EZH2 was mainly expressed in the nuclei of tumor cells, showing pale yellow to brownish yellow granules." (PMID 37198697, 2023). "This transitional cell subpopulation expressed markers such as MYCN, EZH2, and SOX11 and was associated with rapid proliferation and tumour metastasis." (PMID 37887559, 2023). "O-GlcNAcylation of EZH2 at multiple sites, such as S73A, S76A, S84A, T313A, and S729A, enhances its stability and methylation enzyme activity, promoting tumor progression." (PMID 37909018, 2023). "In some tumours, EZH2 can recruit DNA methyltransferases to the promoter regions of related genes, promoting DNA methylation." (PMID 38050190, 2023). "Modification of H3K27me3 in the promoter region of the CDKN2A-2B gene cluster and enrichment of EZH2 were reduced, which increased mRNA levels of the tumor-suppressor genes P14, P15, and P16 and inhibited HCC cell proliferation and migration." (PMID 37268997, 2023). "In prostate cancer, FOXM1 is highly expressed, and its regulation of EZH2 is essential for tumor cell proliferation and progression." (PMID 37686402, 2023). "GSK343 treatment decreased DNMT3A recruitment to the ULBP1 ligand promoter, reducing promoter DNA methylation and increasing ULBP1 expression, further elucidating the role of EZH2 as an inhibitor of anti-tumor immune responses." (PMID 37090711, 2023). "The list of potential tumor suppressor hits included both known factors, such as Ezh2 and Tle4, as well as novel candidates, including Kdm5c, Pcgf3, Chd1 and Pbrm1." (PMID 36631623, 2023).
tumor (continued). "Combined EZH2 knockdown and T/P treatment also synergized to reduce tumor growth and further activate NK and T cell immune responses in established PDAC lung metastases." (PMID 37142692, 2023). "In this study, we observed a significantly higher mRNA expression of EZH2 in most tumor samples in a contrast to non-tumor tissues." (PMID 37689710, 2023). "We proposed that CTD likely inhibits tumour progression by regulating the cell cycle pathway through the EZH2-H3K27me3-dependent gene expression network." (PMID 37202806, 2023). "The expression levels of EZH2 protein were roughly consistent with that of the mRNA levels in both normal and tumor tissues." (PMID 36545914, 2023). "Because EZH2 mediates the inhibition of MHC I/II in microglia, inhibition of EZH2 in microglia restores some of the immunogenicity of the tumor and reinforces the sensitivity to ICB (immune checkpoint blockade)." (PMID 37700840, 2023). "Tumor-bearing mice were treated with tazemetostat, an EZH2 inhibitor, ZA, or a combination of both drugs, and we monitored tumor volume over time." (PMID 36657447, 2023). "In our study, we demonstrated that in OC, EZH2 transcriptionally upregulated IDH2 to potentiate metabolic rewiring by enhancing tricarboxylic acid cycle (TCA cycle) activity, which provide a novel mechanism by EZH2 to promote tumor growth." (PMID 37210576, 2023). "EZH2 is an enzyme subunit of the PRC2 complex that plays an essential role in tumour development through its catalytic and non‐catalytic activities." (PMID 38050190, 2023). "EZH2 was widely expressed in multiple normal and tumor tissues, predominantly located in the nucleoplasm." (PMID 36545914, 2023). "Afterward, the phosphorylation levels of EZH2 at the T487 site were examined and compared between the tumor and adjacent normal tissues." (PMID 36545914, 2023). "Disappointingly, according to the result of a phase Ib study, the combination of PD-L1 inhibitor and EZH2 inhibitor has modest anti-tumor activity in r/r DLBCL." (PMID 36959853, 2023). "Epi-drugs, defined as small-molecule inhibitors that target epigenetic regulators like DNMT, HDAC, and EZH2, have been shown to augment anti-tumor immune responses through multiple immunomodulatory activities." (PMID 37386520, 2023). "The biological function of phosphorylated EZH2 in tumor cells have been increasingly raising concern recently." (PMID 37803297, 2023). "The results showed that CRISPR/Cas9-induced EZH2 gene editing reduced cell growth, migration and invasion in vitro and resulted in a 90% reduction in tumor growth when EZH2-edited cells were injected into an immunocompromised mouse model." (PMID 37175580, 2023). "While the inhibition of such ligands is usually dependent on immune checkpoint monoclonal antibodies or inhibitors, EZH2 small molecule inhibitors are also synergistic and can still promote the apoptosis of tumor cells themselves." (PMID 37239949, 2023). "The interaction of HOTAIR with miR-122 via EZH2-mediated DNA methylation is a unique mechanism of lncRNA–miRNA interaction, contributing to gene regulation in tumor cells." (PMID 37345170, 2023). "Several cancer cell lines proliferate when EZH2 is overexpressed, whereas tumor growth is inhibited by EZH2 suppression." (PMID 38275371, 2023). "High expression of EZH2 was observed in 77.4% (24/31) cases with tumor size > 4 cm while low expression was noted in 41.37% (12/29) cases with tumor size ≤ 4 cm which was statistically insignificant (p = 0.118)." (PMID 37131568, 2023). "On the other hand, EZH2, which serves as an epigenetic modifier that inhibits the expression of tumor suppressors, has been shown as a potential drug target both alone and in the combination with Top2 inhibition." (PMID 36678591, 2023). "MELK and FOXM1 were found to be the predominant activators of EZH2 transcription in these tumor stem cells, and MELK–FOXM1–EZH2 signaling mediated cellular resistance to irradiation." (PMID 37686402, 2023).
tumor (continued). "Overall, our data indicated that the combination of FGFR4 and EZH2 inhibitors can significantly inhibit tumor growth both in vitro and in vivo, which would supply new literatures for the development of clinical treatment strategies for HCC." (PMID 37085881, 2023). "Collectively, our work provides a strategy for leveraging EZH2 inhibitors as an immune oncology approach in combination with senescence-inducing agents to remodel the inflammatory tumor secretome for immune-mediated PDAC control." (PMID 37142692, 2023). "In most situations, EZH2 exhibits carcinogenic effects via H3K27 tri-methylation which turns off the expression of tumor suppressive genes." (PMID 38031139, 2023). "BALB/c nude mice were used to establish a xenograft tumor model and verify the phenotypes upon EZH2 and TOP2A silencing and miR-139 overexpression in vivo." (PMID 38008711, 2023). "In the current study, the tumor suppressor function and regulation of UTX in CRC provide a molecular basis and the rationale to target EZH2 in UTX-deficient CRC." (PMID 37679762, 2023). "We have previously demonstrated that inhibition of EZH2 in a HER2+ mouse model induces tumor cell expression of endogenous retroviral elements that promote expression of IFNs and sensitize tumors to anti-HER2 targeted therapy." (PMID 36910138, 2023). "Compared with adjacent normal tissues, the miR-139-5p level is lower in HCC tumor tissues; compared with low-EZH2 HCC, miR-139-5p expression was lower in high-EZH2 HCC; compared with low-TOP2A HCC, miR-139-5p expression was lower in high-TOP2A HCC." (PMID 38008711, 2023). "Numerous reports indicate the involvement of EZH2 in regulation of tumor microenvironment (TME) and antitumor immune response, which directly affect immunotherapy efficacy." (PMID 37325482, 2023). "EZH2 is the catalytic subunit of polycomb repressive complex 2, which methylates histone H3 lysine 27, silencing a number of tumor-suppressor genes, including E-cadherin." (PMID 36959801, 2023). "In this manner, EZH2 regulates cell cycle progression, proliferation and differentiation of both cancer cells and immune cells, affecting immune surveillance and tumor growth." (PMID 37090711, 2023). "Despite a lack of published data, clinical trials have demonstrated most CH therapies to be repurposed from other neoplasms that share common molecular pathways, with an increased focus on small molecules (TKIs, EZH2 inhibitors) and combination therapeutics." (PMID 38136345, 2023). "Additional investigation is warranted to comprehensively grasp the intricate interplay between EZH2, tumor immunogenicity, and the response to ICIs." (PMID 38077327, 2023). "A peptide of the sequence of YY1’s OPB domain (IR4) was previously shown to inhibit YY1 binding to EZH2, reduce breast cancer cell viability, and efficiently inhibit the growth of a xenograft tumor." (PMID 37686614, 2023). "Numerous studies have shown that EZH2 is involved in a wide range of biological processes, such as tumor development, growth, metastasis, apoptosis, angiogenesis, stem cell renewal/ maintenance, and treatment-resistance." (PMID 37803297, 2023). "In EwS, EWS-FLI1 upregulates EZH2 expression by interacting with the EZH2 promoter, thereby promoting tumor growth/metastasis and blocking endothelial/neuro-ectodermal differentiation." (PMID 37627063, 2023). "EZH2 inhibitors also restore the expression of Th1-type chemokines in ovarian cancer, facilitate tumor infiltration of effector T cells, and enhance the efficacy of anti-PD-L1 treatment." (PMID 37394580, 2023). "It has been shown that inhibiting EZH2 reversed acquired resistance and enhanced anti-tumor effects when in combination with anti-PD1, anti-CTLA-4, and IL-2 immunotherapy in prostate cancer and melanoma." (PMID 37386520, 2023). "Enhancer of Zeste Homolog 2 (EZH2) is a histone methyltransferase and catalyzes methylation of histone H3 and plays an important role in tumor cell proliferation, invasion, and metastasis." (PMID 37131568, 2023).
tumor (continued). "Histone methyltransferase EZH2 functions within the Polycomb Repression Complex 2 to repress transcription of tumor suppressors." (PMID 37686614, 2023). "Yet, RNA immunoprecipitation (RIP) assays have an SNHG15 interaction with EZH2 to repress tumor suppressor genes via EZH2-mediated trimethylation at H3K27 in the nucleus." (PMID 37880732, 2023). "For instance, cluster 10 showed a tumor-promoting role as indicated by the high expression of EZH2, and cluster 0 had high expression level of the transcription factor PPARG that can regulate the production of M2-like macrophages." (PMID 37644609, 2023). "It has been reported that EZH2 played a significant role in multiple tumor progression by affecting cellular senescence." (PMID 36635272, 2023). "Specifically, we show how the mechanism of EZH2 inhibition to enhance tumor immunogenicity in vitro via the upregulation of MHC class 1 is applicable to a pediatric CNS oncologic context." (PMID 38001715, 2023). "Targeting EZH2 for cancer therapy is a current research topic involving tumour immune, tumour metabolism and tumour drug resistance." (PMID 38050190, 2023). "ZFAS1 had a critical role in inhibition of tumor suppressors by EZH2 and LSD1 recruitments in GC cells." (PMID 37807067, 2023). "Striking a delicate balance between anti-tumor and pro-tumor immune responses through pharmacological perturbation of EZH2 is required to achieve therapeutic efficacy." (PMID 36627707, 2023). "In the context of cancer, the role of PRC2, and EZH2 specifically, is multifaceted as it can function both as a tumor-suppressor and as an oncogene in a cell type dependent manner." (PMID 37664059, 2023). "Here, we report that combined EZH2/HDAC inhibitors potently kill CRPCs and cause dramatic tumor regression in aggressive human and mouse CRPC models." (PMID 37104245, 2023). "Although various studies have been investigated in EZH2 behavior in malignancies, few literatures have been focused on the cytoplasm-nucleus sublocation of EZH2 in tumor cells." (PMID 37803297, 2023). "Given that abnormal expression of EZH2 plays an essential role in tumor cell proliferation, invasion, metastasis, and drug resistance, targeted inhibition of EZH2/PRC2 is considered an attractive target for cancer therapy." (PMID 36672374, 2023). "Compared to controls, mice injected with EZH2‐ knockdown CCA cells (shEZH2#1) exhibited significantly slower tumour progression." (PMID 38050190, 2023). "As a new anti‐tumor drug in the epigenetics field, the development of EZH2 inhibitors is at the forefront, and one drug has been listed." (PMID 37220590, 2023). "The EZH2 protein mediates modifications in histone methylation that repress several tumor suppressor genes, as DKKI, CDH1, and DAB2IP." (PMID 37404760, 2023). "The overexpression or enhanced activation of EZH2 results in transcriptional repression of tumour suppressor genes." (PMID 37046649, 2023). "EZH2 has a dual role, as evidenced by its oncogenic role and tumor-suppressive role in different hematologic malignancies." (PMID 36797244, 2023). "For instance, 3-deazaneplanocin A (DZNep) robustly impedes the self-renewal and tumor-forming capabilities of GBM stem cells by inducing pharmacological disruption of EZH2." (PMID 38264522, 2023). "This, and recent studies of the enhanced antitumor immunity with EZH2 inhibitors, highlights the potential of targeting epigenetic mechanisms in tumor therapy." (PMID 37691307, 2023). "The sensitivity of H3K27M DMGs and PFAs to EZH2 inhibition points to a potential role for H3K27me3 in maintaining tumor cell proliferative capacity." (PMID 36759899, 2023). "Meanwhile, the combination of EZH2 inhibitors with proteasome inhibitors to induce tumor regression in vivo, and the feasibility of synthetic dual-target inhibitors, has been put on the agenda, but there is still insufficient evidence for clinical application." (PMID 37239949, 2023).